AGR2 (anterior gradient 2, protein disulphide isomerase family member)
Diseases named in the same sentence as AGR2 in open-access papers (continued):
Sharing a sentence is not in itself a finding about the gene and the disease.
ovarian carcinoma (continued). "The treatment of the ovarian cancer cell line SK-OV-3 with a DNA methyltransferase inhibitor to increase the level of AGR2 expression resulted in increased cell migration and invasion." (PMID 31247903, 2019). "A humanized ɑ-AGR2 (18A4Hu) and its murine version (18A4) alone were reported to have inhibitory effect on AGR2+ ovarian cancer xenograft SK-OV-3." (PMID 31303962, 2019). "In gynecological cancer, overexpression of the AGR2 protein was reported in high-grade ovarian carcinoma, which is related with metastasis and poor prognosis." (PMID 30406031, 2018). "The expression profile of AGR2 and cell cycle proteins here presented was showed as good prognosis marker in epithelial ovarian cancer." (PMID 29845750, 2018). "Currently, relapse in ovarian cancer presents one of the most important limitations in the survival gains of patients, so the evaluation of AGR2 and the proteins of the cell cycle can assistance in the identification of these patients." (PMID 29845750, 2018). "Generally, AGR2 is highly expressed in mucus‐secreting cells and endocrine organs, and in this study, we aimed to evaluate AGR2 and cell cycle molecules in epithelial ovarian cancer and its implications on prognosis." (PMID 29845750, 2018). "The median plasma concentrations of both ir MDK and ir AGR2 were significantly greater in women with ovarian cancer (909 pg/ml and 765 pg/ml, respectively n = 46) than in normal healthy women (383 pg/ml and188 pg/ml, respectively n = 61) (p < 0.001)." (PMID 20525245, 2010). "AGR2 gene expression is significantly increased in ovarian carcinomas, particularly in mucinous tumors." (PMID 20525245, 2010). "Distribution of Ovarian Tumor Types and Stages of ovarian cancer patients used for plasma AGR2 and CA125 measurements." (PMID 20525245, 2010). "The data obtained in this study confirm that both MDK and AGR2 individually display utility as biomarkers for ovarian cancer and that in a multi-analyte panel significantly improve the diagnostic utility of CA125 in symptomatic women." (PMID 20525245, 2010). "The data obtained confirm the utility of both MDK and AGR2 as plasma biomarkers for ovarian cancer and, when combined in a multi-analyte panel, significantly improve the diagnostic efficiency of CA125." (PMID 20525245, 2010). "It is of note, however, that plasma concentrations of MDK and AGR2 display differential responsiveness in women with ovarian cancer when compared to CA125." (PMID 20525245, 2010). "A clinical study using multiple biomarkers for the early diagnosis of ovarian cancer reported that AGR2 could be used as a biomarker for early ovarian cancer detection." (PMID 41518408, 2026). "Additionally, etravirine decreased the AGR2 levels in ovarian cancer cells in a dose- and time-dependent manner." (PMID 35055132, 2022). "Numerous reports have indicated that AGR2 promotes cell migration and invasion, and we found that etravirine could suppress AGR2 expression in ovarian cancer." (PMID 35055132, 2022). "Moreover, the stable overexpression of AGR2 in human ovarian carcinoma cells (MDAH 2774, derived from ascitic fluid) enhanced cell growth and migration of MDAH 2774 cells." (PMID 34452625, 2021). "The identification of elevated plasma concentrations of AGR2 may provide a useful biomarker to aid in the discrimination of normal and ovarian cancer patients particularly." (PMID 34200338, 2021). "Indeed, undetectable expression was observed in cultures of human clear cell ES-2 carcinoma or in ES-2 xenograft tumours, whereas both cultured human ovarian carcinoma A2780 cells and A2780 xenograft tumours express significant amounts of AGR2." (PMID 34452625, 2021).
ovarian carcinoma (continued). "AGR2 was found to be secreted in the cultured media of pancreatic, breast, lung, gastric, prostate, colorectal and ovarian cancer cells, implying that overexpression of AGR2 in cancers may be linked to its secretion." (PMID 33005802, 2020). "Here, we observed that the lower levels of AGR2 protein in ovarian carcinoma were correlated with high‐grade serous carcinoma and characteristics of malignancy, such as lymphatic vascular invasion, bilateral involvement, necrosis, ovarian surface involvement, lymph node metastasis, and relapse." (PMID 29845750, 2018). "More recently, a role for AGR2 in the aetiology of ovarian epithelial cancer has been proposed." (PMID 20525245, 2010). "The purpose of this study was to characterise changes in the plasma concentrations of MDK in association with ovarian cancer and compare its diagnostic performance (as assessed by the AUC) with that of AGR2 (a recently reported circulating biomarker of ovarian cancer) and CA125 in symptomatic women." (PMID 20525245, 2010). "Targeting the link between ovarian cancer, esophageal squamous cell carcinoma, and other cancers with AGR2 immunity, we can hypothesize that AGR2 influences the immune microenvironment of patients, suggesting a potential undiscovered link between the two that may impact patient prognosis." (PMID 39062458, 2024). "The data obtained in this study confirm that the measurement of plasma concentrations of MDK and AGR2 individually display utility as biomarkers for ovarian cancer and that when included in a multi-analyte panel may significantly improve the diagnostic utility of CA125 in symptomatic women." (PMID 20525245, 2010). "In addition, AGR2 has been reported to be released into the circulation of ovarian cancer patients." (PMID 20525245, 2010). "Plasma AGR2 concentrations were highest in stages II and III ovarian cancer patients and were similarly elevated in patients with both serous and non-serous tumors." (PMID 34200338, 2021). "Available data are consistent with a putative role for both AGR2 and MDK in oncogenesis and tumor progression, including ovarian cancer." (PMID 20525245, 2010). "In particular, elevated levels of AGR2, GLY, FOLR1, and SMRP in ovarian cancer suggest that simultaneous measurement of these markers may enable early diagnosis." (PMID 41518408, 2026). "For instance it would be interesting to investigate whether the different expression patterns of AGR3 and AGR2 in mucinous and non-mucinous (serous, endometrioid and clear cell) ovarian carcinomas could be correlated with patient prognosis." (PMID 34452625, 2021).
colorectal cancer (20 papers, 2012 to 2025). A primary or metastatic malignant neoplasm that affects the colon or rectum. "For instance, M2 tumor-associated macrophages stimulate tumor angiogenesis and contribute to immunosuppressive tumor microenvironment and colorectal cancer metastasis could be promoted by AGR2 from tumor-associated neutrophils." (PMID 37338527, 2023). "In colorectal cancer cells, AGR2 overexpression can be stimulated by prostaglandin E2 (PGE2), released by tumour-infiltrating macrophages, which activates the EP4–PI3K–AKT signalling pathway." (PMID 40767982, 2025). "There is evidence that AGR2 can regulate EMT in colorectal cancer through its interaction with KDELRs, owing to its KTEL retention motif." (PMID 40767982, 2025). "This study was based on whole-proteome analysis of colorectal cancer cell lines with manipulated AGR2 expression." (PMID 39300184, 2024). "Early in vitro studies using dendritic cells indicated that introducing the AGR2 gene into these cells resulted in beneficial effects in targeting colorectal cancer (CRC)." (PMID 39062458, 2024). "Despite the available research, its precise molecular mechanisms, especially the role of AGR2 in colorectal cancer, remain to be elucidated." (PMID 39300184, 2024). "Loss of SMAD4 is a hallmark of PDAC and other gastrointestinal tumor types, like colorectal cancer (CRC), and has been linked to AGR2 up-regulation." (PMID 39727484, 2024). "Another type of innate immune cell, neutrophils promote colorectal cancer metastasis by secreting AGR2 has also been identified." (PMID 37525242, 2023). "In colorectal cancer cells, AGR2 exon 2 knockout was shown to be crucial for protein-mediated cell adhesion, and resulted in the increase of reaction oxygen species production." (PMID 36482387, 2022). "In colorectal cancer cells, AGR2 was also shown to be a potentially useful antigenic target for cancer immunotherapy." (PMID 31247903, 2019). "Human colorectal cancer cell lines that have a high AGR2 expression were targeted using dendritic cells (DCs) that express the AGR2 gene (AdAGR2)." (PMID 31247903, 2019). "Furthermore, studies have highlighted the role of AGR2 in colorectal cancer liver metastasis, where AGR2 secreted by tumor neutrophils contributes to metastatic HCC through the AGR2-CD98HC-xCT axis." (PMID 39062458, 2024). "Therefore, in addition to the lung adenocarcinoma cell line A549, we also analyzed the potential relationship between AGR2 and cyclooxygenases in the colorectal carcinoma cell line HT-29." (PMID 36142758, 2022). "However, a recent study in colorectal cancer reported that AGR2 can be moderately regulated by DNA methyltransferase 3a (DNMT3a) by directly methylating AGR2 promoter or indirectly via the DNMT3a–SPRY2–miR-194 axis." (PMID 33005802, 2020). "In 54 colorectal cancer samples and 19 controls, the results obtained through a real-time polymerase chain reaction (RT-PCR) significantly revealed an enhanced expression of AGR2 mRNAs compared with the controls." (PMID 31247903, 2019). "We aim to estimate the diagnostic performances of anterior gradient homolog-2 (AGR2) and Leucine-rich repeat-containing-G-protein-coupled receptor 5 (LGR5) in peripheral blood (PB) as mRNA biomarkers in colorectal cancer (CRC) and to explore their prognostic significance." (PMID 22605983, 2012). "AGR2 expression was inversely related to SMAD4 status in PDAC and colorectal cancer cell models and was secreted from cells into their media." (PMID 39727484, 2024).
colorectal cancer (continued). "Taken together, our proteomic screen suggests a common mechanism of AGR2 acting over FLNA and NPM3 proteins in SW480 and SW620 colorectal cancer cell models, as demonstrated by both the overexpression and silencing of AGR2." (PMID 39300184, 2024). "CD98hc, expressed in colorectal cancer (CRC) cells, is the functional receptor for secreted AGR2 and physically interacts with AGR2 via its extracellular region." (PMID 37823053, 2023). "Despite extensive research, the molecular role of AGR2 in the progression and metastasis of colorectal cancer (CRC) has not been fully characterized." (PMID 39300184, 2024). "DCs pulsed with the mentioned peptides were used to activate the specific CTLs in AGR2-positive and -negative colorectal cancer cell lines." (PMID 31247903, 2019). "Moreover, AGR2 has been included in the molecular signature that defined CTC in metastatic breast, prostate and colorectal cancers." (PMID 22605983, 2012).
lung adenocarcinoma (20 papers, 2014 to 2025). A carcinoma that arises from the lung and is characterized by the presence of malignant glandular epithelial cells. "Studies evaluating larger cohorts of cancers by immunohistochemistry (IHC) have identified associations between high AGR2 expression and unfavorable tumor phenotype or poor prognosis in adenocarcinoma of the lung, gastric adenocarcinoma, and adenocarcinoma of the prostate." (PMID 39533806, 2024). "miR-199a-3p was also found to bind directly to the 3′-UTR of the AGR2 gene to repress the proliferation of non-small cell lung carcinoma PC-9 and lung adenocarcinoma Calu-3 cells and to induce cancer cell apoptosis." (PMID 40867591, 2025). "RNA-Seq was performed on three pairs of lung adenocarcinoma and adjacent normal lung tissues and identified 9 upregulated genes in which AGR2 were among these upregulated genes." (PMID 33005802, 2020). "An increased AGR2 expression was also illustrated in 147 cases of surgically resected lung adenocarcinomas that had epidermal growth factor receptor (EGFR) gene mutations." (PMID 31247903, 2019). "To test the relevance of AGR2 overexpression in tumorigenesis, we silenced its expression in lung adenocarcinoma cell lines (A549, H23 and H1838) using lentivirus-mediated infection with AGR2 shRNA (Sh-AGR2)." (PMID 27240165, 2016). "With iTRAQ, anterior gradient homolog 2 (AGR2) was identified as overexpressed in lung adenocarcinoma tissues." (PMID 24550697, 2014). "AGR2 knockout inhibited TGF-β-induced EMT in lung adenocarcinoma." (PMID 39682235, 2024). "Our data mining in public databases revealed a higher AGR2 expression in lung adenocarcinomas as compared to normal lung tissues, which may instantly suggest that AGR2 plays an oncogenic role in lung carcinogenesis." (PMID 32570918, 2020). "Besides, gene expression analysis using the Oncomine database that consists of 7 datasets showed similar upregulation of AGR2, suggesting that AGR2 overexpression supports lung adenocarcinoma pathogenesis." (PMID 33005802, 2020). "Studies on lung adenocarcinoma samples showed variable levels of AGR2 expression." (PMID 31247903, 2019). "eIF3i, HSC71, MHC class I antigen, transketolase, citrate synthase, Rab-37, MLH1 and AGR2 might be putative biomarkers in HSP90 inhibition response in lung adenocarcinoma." (PMID 31370342, 2019). "In our study, we found that AGR2 may serve as a potential prognostic biomarker of lung adenocarcinoma." (PMID 29285217, 2017). "For instance, in lung adenocarcinoma and pancreatic ductal adenocarcinoma, TGF-β downregulates AGR2 expression to promote EMT, while in colon and head and neck squamous cell carcinomas, AGR2 overexpression plays a role in EMT promotion." (PMID 39062458, 2024). "In the present study, we show an inverse correlation of AGR2 with ZEB1 (zinc finger enhancer binding protein, δEF1) that was verified by analysis of several independent clinical data sets of lung adenocarcinomas." (PMID 32570918, 2020). "In addition, factors previously identified to be specific markers of lung adenocarcinoma were upregulated, including PROM2, CLDN3, and TJP3, as were genes proposed to have potential diagnostic or prognostic value in human cancers, including MMP9, AGR2, SULF1, NHSL1, LGR5, MUC1, and PIK3C2G." (PMID 31434729, 2019). "In the GSE10072 array, we also observed that expression levels of AGR2 and CLDN3 are significantly upregulated in lung adenocarcinoma when compared to normal lung tissue." (PMID 29285217, 2017). "With higher occurrences, the correlation of differential gene expression and aberrant DNA methylation of AGR2, CDH13, and MX2 have been reported relevant to lung adenocarcinoma." (PMID 27610367, 2016). "Similarly, in lung adenocarcinoma (LUAD), miR-199a-3p targets anterior gradient 2 (AGR2), suppressing tumorigenesis and promoting apoptosis." (PMID 41329722, 2025).
lung adenocarcinoma (continued). "Similarly, in human lung adenocarcinoma, TGF‐β‐induced EMT leads to dramatic down regulation of AGR2, whereas forced overexpression of AGR2 largely reversed the TGF‐β‐induced EMT‐phenotype." (PMID 36329620, 2023). "In the present work, we demonstrate for the first time that AGR2 and ZEB1 expression shows an inverse correlation in lung adenocarcinomas, since AGR2 is usually overexpressed in tumor tissue as compared to the normal tissues, while ZEB1 shows the opposite trend." (PMID 32570918, 2020). "Similar outputs were also obtained by data mining from The Cancer Genome Atlas (TCGA) cohorts for lung adenocarcinoma, demonstrating a significant negative correlation between AGR2 and ZEB1 (p < 0.001)." (PMID 32570918, 2020). "Moreover, we examined the expression of AGR2 and ZEB1 in normal lung tissues and lung adenocarcinoma tissues using the public database Oncomine." (PMID 32570918, 2020). "The analysis of the effects from each gene expression on survival outcome indicated that 6 genes (AGR2, SPDEF, CDKN2A, CLDN3, SFN, and PHLDA2) play oncogenic roles, and 7 genes (PDK4, FMO2, CPED1, GNG11, IL33, BTNL9, and FABP4) act as tumor suppressors in lung adenocarcinoma." (PMID 29285217, 2017).